EDIL3 (EGF like and discoidin domains 3)
Diseases named in the same sentence as EDIL3 in open-access papers (continued):
Sharing a sentence is not in itself a finding about the gene and the disease.
diabetes (4 papers, 2010 to 2023). "API5, EDIL3, BFSP2, HNMT, and SCYL1BP1 were also among the top signals from the single-marker analysis within their associated region, but there is no clear connection currently between these genes and diabetes or its complications." (PMID 20871662, 2010).
osteoarthritis (4 papers, 2016 to 2025). A noninflammatory degenerative joint disease occurring chiefly in older persons, characterized by degeneration of the articular cartilage, hypertrophy of bone at the margins and changes in the synovial membrane. "NID2 and EDIL3 are more frequently associated with cartilage than tendon, but both protect chondrocytes against osteoarthritis." (PMID 40224957, 2025). "Moreover, Edil3-deficient mice develop more severe osteoarthritis compared to control mice that is associated with increased susceptibility of chondrocytes to apoptosis." (PMID 30716086, 2019). "Higher levels of GREM1 and S100A6, however, correlate with osteoarthritis, opposing the expression of NID2 and EDIL3." (PMID 40224957, 2025).
triple-negative breast carcinoma (4 papers, 2019 to 2026). An invasive breast carcinoma which is negative for expression of estrogen receptor (ER), progesterone receptor (PR), and human epidermal growth factor receptor 2 (HER2). "Triple-negative breast cancer (TNBC) lacks effective targeted therapies, and the mechanisms by which developmental endothelial locus-1 (EDIL3/Del-1) promotes TNBC remain incompletely defined." (PMID 41898541, 2026).
glioblastoma (3 papers, 2015 to 2023). The most malignant astrocytic tumor (WHO grade IV). "In MG3, genes involved in endothelial regulation (ESM1, APLN, ALCAM) and ligands for αVβ3 integrin (EDIL3 and POSTN) were expressed at higher levels compared to MG1 and MG5, the latter of which recruit tumour-associated macrophages (TAM) in adult glioblastoma." (PMID 37679810, 2023).
lung carcinoma (3 papers, 2017 to 2022). "The overexpression of EDIL3 was observed in several tumor types, including breast, bladder, liver, and lung carcinomas, and it associates with drug resistance and poor prognosis." (PMID 35096599, 2021).
pancreatic cancer (3 papers, 2014 to 2021). "In the present study, we performed investigations to determine (a) the expression pattern and clinical significance of EDIL3 in pancreatic cancer, (b) the underlying roles of EDIL3 in pancreatic cancer cells, and (c) possible mechanism involved in EDIL3-mediated functions." (PMID 26735172, 2016). "Our present findings indicate that EDIL3-related pathway plays an important role in progression of human pancreatic cancer." (PMID 26735172, 2016). "However, little is known about the expression pattern and cellular functions of EDIL3 in pancreatic cancer." (PMID 26735172, 2016). "This newly identified EDIL3/Bcl-2 axis might provide a further insight into the pathogenesis of pancreatic cancer and indicate a novel approaches that can be used for the treatment of pancreatic cancer." (PMID 26735172, 2016). "Consistent with the findings in PDAC tissues, EDIL3 expression was remarkably up-regulated in all of six pancreatic cancer cell lines in relative to the nonmalignant hTERT-HPNE cells at both mRNA level, protein level and secreted level." (PMID 26735172, 2016). "In conclusion, this study provides evidences that EDIL3 is a potential predictor and plays an important role in anchorage independent tumor growth of PDAC and EDIL3-related pathways might represent a novel therapeutic strategy for treatment of pancreatic cancer." (PMID 26735172, 2016).
psoriasis (3 papers, 2021 to 2022). An autoimmune condition characterized by red, well-delineated plaques with silvery scales that are usually on the extensor surfaces and scalp. "So, this study aimed to explore the association between EDIL3 derived from DMSCs (DMSCs‐derived EDIL3) and psoriasis‐associated angiogenesis." (PMID 36065978, 2022). "Our data indicated that DMSCs‐derived EDIL3 contributed to activating ECs properties, then promoted tube‐structure formation and caused angiogenesis in dermal of psoriasis." (PMID 36065978, 2022). "First, we injected recombinant EDIL3 protein to mouse model of psoriasis to confirm the roles of EDIL3 in psoriasis." (PMID 36065978, 2022). "And interesting, IMQ + EDIL3‐induced psoriasis‐like lesion in mouse model resulted in higher epidermis thickness compared with the IMQ + NS‐treated (p < 0.05)." (PMID 36065978, 2022). "We injected recombinant EDIL3 protein to mouse model of psoriasis to confirm the roles of EDIL3 in psoriasis." (PMID 36065978, 2022). "To further explore the role of EDIL3 in psoriasis, in present study, we detected the epidermis thickness and microvessel density in IMQ‐induced mouse model through injecting EDIL3." (PMID 36065978, 2022). "Together, these data suggested that the upregulation of EDIL3 can promote microvascular formation in development of psoriasis." (PMID 36065978, 2022). "The results suggested that EDIL3 accelerated the process of psoriasis through induce angiogenesis of microvascular." (PMID 36065978, 2022). "Our prior study demonstrated the mRNA and protein expression of EDIL3 in DMSCs was significantly upregulated in psoriasis." (PMID 36065978, 2022). "Recently, epidermal growth factor-like repeats and the discoidin I-like domain 3 (EDIL3) were reported to be highly expressed in the dermal mesenchymal stem cells of psoriasis." (PMID 34769465, 2021). "Besides, we employed both short‐interference RNA (si‐RNA) and lentiviral vectors to explore the molecular mechanism of EDIL3 promoting angiogenesis in psoriasis." (PMID 36065978, 2022). "The essential step in occurrence and development of psoriasis, based on this, we speculated that EDIL3 and αvβ3‐FAK/MEK/ERK signal pathway will provide a valuable therapeutic target to control angiogenesis." (PMID 36065978, 2022). "In present study, we found EDIL3 accelerated the process of psoriasis in vivo." (PMID 36065978, 2022). "In vitro, EDIL3 derived from DMSCs (DMSCs‐derived EDIL3) in psoriasis promotes angiogenesis of ECs." (PMID 36065978, 2022). "Based on previous studies, we found the DMSCs and EDIL3 play an important role in psoriasis." (PMID 36065978, 2022). "EDIL3 accelerated the process of psoriasis in the IMQ‐induced psoriasis‐like mouse model." (PMID 36065978, 2022). "To explore whether EDIL3 accelerated the pathological progress of psoriasis is also through modulated angiogenesis, we conducted IF analysis." (PMID 36065978, 2022). "And the modification of DMSCs, EDIL3 and αvβ3‐FAK/MEK/ERK signal pathway will provide a valuable therapeutic target to control the angiogenesis in psoriasis." (PMID 36065978, 2022). "This suggested that DMSCs‐derived EDIL3 and αvβ3‐FAK/MEK/ERK signal pathway in ECs play an important role in the pathogenesis of psoriasis." (PMID 36065978, 2022). "This suggested that EDIL3 from DMSCs and αvβ3‐FAK/MEK/ERK signal pathway in ECs play an important role in the pathogenesis of psoriasis." (PMID 36065978, 2022). "Therefore, EDIL-3 may play a role in the angiogenesis of psoriasis." (PMID 34769465, 2021).
lung adenocarcinoma (2 papers, 2017 to 2021). A carcinoma that arises from the lung and is characterized by the presence of malignant glandular epithelial cells. "Thirdly, this study revealed that EDIL3 expression is significantly associated with tumor angiogenesis, characterized by microvessel density in lung adenocarcinoma tissue." (PMID 28819306, 2017). "In lung adenocarcinoma patients, EDIL3 was an independent prognostic factor for overall survival in a multivariate analysis (hazard ratio: 2.552, P = 0.004)." (PMID 28819306, 2017). "In lung adenocarcinoma patients, EDIL3 expression was significantly correlated with low e-cadherin expression, high vimentin expression, and increased microvessel density (P < 0.001, P = 0.001, and P = 0.023, respectively)." (PMID 28819306, 2017). "EDIL3 is significantly correlated with mesenchymal phenotype, angiogenesis, and tumor progression in lung adenocarcinoma." (PMID 28819306, 2017). "Fourthly, our study demonstrates that EDIL3 expression has prognostic value in lung adenocarcinoma." (PMID 28819306, 2017). "The EDIL3/EMT/angiogenesis pathway may provide further insight into tumor progression in lung adenocarcinoma." (PMID 28819306, 2017). "In conclusion, EDIL3 overexpression is an independent negative prognostic factor for OS in lung adenocarcinoma." (PMID 28819306, 2017).
lung squamous cell carcinoma (2 papers, 2017 to 2025). "In lung squamous cell carcinoma patients, EDIL3 expression was significantly correlated with low e-cadherin expression and high vimentin expression (P = 0.021 and P = 0.002, respectively)." (PMID 28819306, 2017).
lymph node metastasis (2 papers, 2016 to 2023). "Multivariate Cox analysis demonstrated that lymph node metastasis, pTNM stage, and EDIL3 expression were independent factors of OS in our cohort." (PMID 37576496, 2023). "Univariate Cox analysis showed that serosal invasion, lymph node metastasis, pTNM stage, and EDIL3 expression were notably correlated with OS in GC." (PMID 37576496, 2023). "Meanwhile, a multivariate Cox regression analysis identified that EDIL3 expression, age, lymph node metastasis and histological differentiation as independent predictors of the overall survival in patients with PDAC." (PMID 26735172, 2016). "Univariate Cox regression analyses showed that EDIL3 expression, age, TNM stage, tumor size, lymph node metastasis, distant metastasis and histological differentiation were significantly associated with overall survival." (PMID 26735172, 2016).
myocardial infarction (2 papers, 2023 to 2025). Gross necrosis of the myocardium, as a result of interruption of the blood supply to the area, as in coronary thrombosis. "EDIL3 was negatively associated with neutrophil recruitment and macrophage expansion in myocardial infarction (MI)." (PMID 36859358, 2023).
non-small cell lung carcinoma (2 papers, 2017 to 2023). A group of at least three distinct histological types of lung cancer, including non-small cell squamous cell carcinoma, adenocarcinoma, and large cell carcinoma. "We examined the prognostic significance of Epidermal Growth Factor-like repeats and Discoidin I-Like Domains 3 (EDIL3) expression and its correlations with mesenchymal phenotype and microvessel density in non-small cell lung carcinoma (NSCLC)." (PMID 28819306, 2017).
aneurysm (1 paper, 2020). Bulging or ballooning in an area of an artery secondary to arterial wall weakening. "The co-occurrence of intracranial and extracranial aneurysms in subject IA10 may suggest an overlapping pathogenesis of intracranial and extracranial vascular diseases, as already reported by others, and may reflect the general importance of EDIL3 for vascular integrity." (PMID 32367296, 2020).
arrhythmogenic right ventricular cardiomyopathy (1 paper, 2023). "KEGG pathway analysis indicated that EDIL3 co-expressed genes were mainly enriched in ECM-receptor interaction, arrhythmogenic right ventricular cardiomyopathy, complement and coagulation cascades, dilated cardiomyopathy (DCM), and focal adhesion." (PMID 37576496, 2023).
bladder tumor (1 paper, 2025). "For instance, the protein EDIL-3/Del1, secreted by bladder tumor cells within exosomes, accelerates tumor progression by promoting cell adhesion and migration." (PMID 40693234, 2025).
chronic pancreatitis (1 paper, 2016). A chronic inflammatory process causing damage and fibrosis of the pancreatic parenchyma. "In the commercial TMA (TMA1, OD-CT-DgPan01-006), we found that EDIL3 was significantly up-regulated in chronic pancreatitis (CHP) tissues and PDAC tissues compared with normal pancreas (NP)." (PMID 26735172, 2016).
COVID-19 (1 paper, 2022). A disease caused by infection with severe acute respiratory syndrome coronavirus 2. "Therefore, our result, conforming with previous reports, indicates that simultaneous upregulation of CD40, Flt3L, IL-6, IL-8, and LIF, in association with CAPG and EDIL3, plays a pivotal role in inflammation and recruitment of immune cells in lung tissues of COVID-19 patients." (PMID 36428847, 2022). "Particularly, this study reports upregulated ADA, BTC, DPP6, EDIL3, LIF, ENTPD2, Flt3L, and LRP1 in severe COVID-19 patients for the first time." (PMID 36428847, 2022). "Furthermore, this study reports markers including ADA, BTC, DPP6, EDIL3, LIF, ENTPD2, Flt3L, and LRP1 to be upregulated in severe COVID-19 patients; hence, they are proposed as novel biomarkers for severe cases of COVID-19." (PMID 36428847, 2022).
endometrial cancer (1 paper, 2023). Primary or metastatic malignant neoplasm involving the endometrium (mucous membrane that lines the endometrial cavity). "The study showed a positive correlation between EDIL3 overexpression and cancer grade, with the greatest difference in expression occurring between G1 and G3 endometrial cancer." (PMID 36982551, 2023). "Overexpression of EDIL3 could distinguish normal endometrium from G1 endometrial cancer and could also be used as an adverse prognostic factor." (PMID 36982551, 2023). "In the control group (patients without neoplastic changes), higher levels of EDIL3 occurred in glandular cells, whereas in the study group (patients with G1, G2, and G3 endometrial cancer), they occurred in cancer cells." (PMID 36982551, 2023).
gastric cancer (1 paper, 2023). A primary or metastatic malignant neoplasm involving the stomach. "However, the biological function of EDIL3 in gastric cancer (GC) is still unclear." (PMID 37576496, 2023).
liver disease (1 paper, 2024). "A subsequent genome-wide association study (GWAS) identified shared single-nucleotide polymorphisms (SNPs) in the genes AR, EDIL3, MACROD2, PCSK5, RUNX1T1, TENM4, and ZEB2 between PN and liver disease from the FinnGen cohort." (PMID 38397136, 2024).
Moyamoya disease (1 paper, 2013). Moyamoya disease (MMD) is a rare intracranial arteriopathy involving progressive stenosis of the cerebral vasculature located at the base of the brain causing transient ischemic attacks or strokes. "Using the novel functional interpolating single-nucleotide polymorphisms bioinformatics approach, we identified 6 Moyamoya Disease-associated autoantibodies against APP, GPS1, STRA13, CTNNB1, ROR1 and EDIL3." (PMID 23518061, 2013).
mucinous adenocarcinoma (1 paper, 2017). An invasive adenocarcinoma composed of malignant glandular cells which contain intracytoplasmic mucin. "In this study, groups that expressed EDIL3 were more likely to have the mucinous adenocarcinoma subtype than were EDIL3-negative groups." (PMID 28819306, 2017). "Patients with EDIL3 expression were more likely to have the mucinous adenocarcinoma subtype (17.6% vs. 2.3%) and less likely to have the solid adenocarcinoma subtype (11.8% vs. 22.1%) than were EDIL3-negative patients (P = 0.004)." (PMID 28819306, 2017).
parasite infection (1 paper, 2022). "Considering these functions, EDIL3 protein could have potential consequences on the initiation, sustainment and/or resolution of inflammation during GIN parasite infection in sheep." (PMID 35360858, 2022).
squamous cell carcinoma (1 paper, 2017). A carcinoma arising from squamous epithelial cells. "The percentage of EDIL3 positivity was also significantly higher in adenocarcinoma than in squamous cell carcinoma (21% vs. 8%, p = 0.01)." (PMID 28819306, 2017). "The number of EDIL3-positive patients with adenocarcinoma and squamous cell carcinoma was 35/166 (21.1%) and 9/102 (8.8%), respectively." (PMID 28819306, 2017). "A further large-scale study is needed to evaluate the roles of EDIL3 and vimentin in squamous cell carcinoma." (PMID 28819306, 2017). "The number of patients with squamous cell carcinoma was relatively small and the incidence of EDIL3+ or Vimentin+ was low." (PMID 28819306, 2017). "In squamous cell carcinoma patients, EDIL3 expression was significantly correlated with low e-cadherin expression (P = 0.021) and high vimentin expression (P = 0.002)." (PMID 28819306, 2017). "However, in squamous cell carcinoma patients, EDIL3 positivity was not significantly (P = 0.488) associated with OS." (PMID 28819306, 2017).